PCDHB4 (protocadherin beta 4)
Description:
Potential calcium-dependent cell-adhesion protein. May be involved in the establishment and maintenance of specific neuronal connections in the brain.
Synonyms: PCDH-BETA4
Tractability: Antibody: its Gene Ontology location is reachable by antibodies, with high confidence; UniProt places it where antibodies can reach, with medium confidence; UniProt predicts a signal peptide or a membrane-spanning region; the Human Protein Atlas places it where antibodies can reach. PROTAC: ubiquitination databases record sites on it.
Gene: Protein-coding gene on chromosome 5 (141,121,818 to 141,125,623, forward strand). Ensembl gene ENSG00000081818.
Subcellular location: Cell membrane
Subcellular location (Human Protein Atlas): Plasma membrane; Nuclear membrane
Gene Ontology:
Molecular function: cell adhesion molecule binding; calcium ion binding
Biological process: calcium-dependent cell-cell adhesion; cell adhesion; chemical synaptic transmission; nervous system development; synapse assembly; homophilic cell-cell adhesion
Cellular component: membrane; plasma membrane; synapse
Genetic constraint (gnomAD): Loss-of-function variants: 1 observed, 0.39 expected, observed/expected ratio (o/e) 2.55. That is too few expected variants to judge how well the gene tolerates losing a copy. Missense variants: 1,063 observed, 1,026.2 expected, observed/expected ratio (o/e) 1.04, 90% interval 0.98 to 1.09. Synonymous variants: 482 observed, 450.18 expected, observed/expected ratio (o/e) 1.07, 90% interval 0.99 to 1.15.
Homologues: Orthologues: macaque PCDHB4 (96% identical), dog PCDHB4 (86% identical), mouse Pcdhb5 (79% identical), mouse Pcdhb7 (78% identical), rat Pcdhb7 (78% identical), mouse Pcdhb9 (77% identical), rabbit PCDHB4 (73% identical), chimpanzee PCDHB4 (68% identical), guinea pig PCDHB4 (67% identical). Paralogues in human: PCDHB5 (77% identical), PCDHB6 (77% identical), PCDHB15 (76% identical), PCDHB3 (75% identical), PCDHB14 (75% identical), PCDHB12 (74% identical), PCDHB2 (74% identical), PCDHB7 (74% identical), PCDHB11 (74% identical), PCDHB8 (74% identical), PCDHB16 (74% identical), PCDHB13 (73% identical), and 49 more.
Diseases named in the same sentence as PCDHB4 in open-access papers:
PCDHB4 is named in the same sentence as 10 diseases in open-access papers, as found by Europe PMC text mining. Sharing a sentence is not in itself a finding about the gene and the disease. The quoted sentences say what the papers report.
autism spectrum disorder (1 paper, 2015). A spectrum of developmental disorders that includes autism, and Asperger syndrome. "De novo mutations in Pcdhb4, which was found in our deregulated list, have been associated with sporadic autism spectrum disorders." (PMID 26035870, 2015).
Brain atrophy (1 paper, 2017). Partial or complete wasting (loss) of brain tissue that was once present. "Patients, whose clinical phenotype is featured by global developmental delay and brain atrophy, have mutation in PCDHB4 (NM_021908:c.489T>G:p.Y163X) based on the candidate gene analysis, and the function of which participated in the growth and development process." (PMID 29291004, 2017).
cervical cancer (1 paper, 2013). A primary or metastatic malignant neoplasm involving the cervix. "Among the 49 PRC2 targets (defined by consistent hyper-MVPs) identified here were 10 genes of the cadherin superfamily in HPV+ HNSCC, including CDH8 and CDH13 (both also hypermethylated in cervical cancer, CDH18, CDH19, CDH23, PCDH10, PCDH15, PCDHB1, PCDHB4, and PCDHB15." (PMID 23419152, 2013).
Tetralogy of Fallot (1 paper, 2017). A congenital cardiac malformation comprising pulmonary stenosis, overriding aorta, ventricular septum defect, and right ventricular hypertrophy. "Analysis using Gene Ontology /pathway, Online Mendelian Inheritance in Man, PubMed and other databases revealed that PEX5, NACA, ATXN2, CELA1, PCDHB4 and CTBP1 were associated with Tetralogy of Fallot." (PMID 29291004, 2017). "Our findings identify PEX5, NACA, ATXN2, CELA1, PCDHB4 and CTBP1 mutations as underlying genetic causes of isolated tetralogy of Fallot." (PMID 29291004, 2017).
cancer (2 papers, 2015 to 2025). A tumor composed of atypical neoplastic, often pleomorphic cells that invade other tissues. "Expression validation in the transcriptome, TCGA–BLCA, and GSE13507 datasets confirmed the up-regulation of APOL1, DHX34, and TNK2, and the down-regulation of AHNAK, CSPG4, NCAM1, and PCDHB4 in the cancer group." (PMID 40908816, 2025).
tumor (2 papers, 2022). "In this study, PCDHB2, PCDHB4, and PCDHB6 were overexpressed in the HCCW4 subgroup, in association with worse survival; this finding contradicts a tumor suppressor role." (PMID 36230503, 2022).
PCDHB4 also shares sentences with these, for which no sentence is quoted: autism (1 paper); breast carcinoma (1); developmental delay (1); epilepsy (1).